ICAM1 (intercellular adhesion molecule 1)
Diseases named in the same sentence as ICAM1 in open-access papers (continued):
Sharing a sentence is not in itself a finding about the gene and the disease.
tumor (continued). "A key player in this step of the metastatic cascade is ICAM-1, of which we confirmed a higher expression in the isolated Fra-2 cl 2 scid primary tumours by Western blot and IHC analysis." (PMID 34693476, 2022). "nucleatum in tumor tissues of CRC patients was positively associated with the expression levels of ALPK1 and ICAM1." (PMID 35220887, 2022). "As important support of this model, we have obtained recently published data showing that CAR T efficacy is strongly dependent on the level of tumor cell ICAM-1." (PMID 35681548, 2022). "This analysis predicted that tumor-specific FAP+ fibroblasts likely originated from FGFR2+ fibroblasts or ICAM1+ telocytes." (PMID 35365629, 2022). "Targeting vimentin induces a pro-inflammatory condition in the tumor, exemplified by induction of the endothelial adhesion molecule ICAM1, suppression of PD-L1, and altered immune cell profiles." (PMID 35606362, 2022). "The patients with increased ICAM-1 expression have more advanced stage, as it promotes the tumor growth." (PMID 36505809, 2022). "CircRNA is also involved in tumor immunity by regulating intercellular cell adhesion molecule-1 (ICAM-1) molecules." (PMID 35464462, 2022). "During this process, tumor cells secrete factors such as IL-8 to promote the leukocyte expression of adhesion receptors like β2-integrin, that can bind directly to ICAM-1 and E-selectin, present on endothelial cells." (PMID 35207611, 2022). "Anti-tumor N1 TANs possess high levels of TNFα, CCL3, ICAM-1, and are also involved in the production of ROS which is cytotoxic to tumor cells." (PMID 36253762, 2022). "ICAM-1 plays a key role in tumor progression and prognosis, partly because it enhances the metastatic ability of malignant tumors." (PMID 35741337, 2022). "The adaptive immune arm was also suggested to use cancer cell–expressed ICAM-1 for tumor elimination." (PMID 35911772, 2022). "Although ICAM1 (intercellular adhesion molecule 1) is ubiquitous on the cell surface, its overexpression in several cancers promotes tumor cell invasion and metastasis and is inversely connected with patient prognosis." (PMID 35982458, 2022). "Tumor vasculature is an important physical barrier for T cells due to the imbalance of adhesion molecules, such as intercellular adhesion molecule 1 (ICAM1), vascular cell adhesion protein 1 (VCAM1), and mucosal addressing cell adhesion molecule 1 (MAdCAM1)." (PMID 35296094, 2022). "Radiation induces increased expression of vascular cell adhesion molecule 1 (VCAM-1) and intercellular adhesion molecule 1 (ICAM1) in tumor vessels, thereby promoting tumor infiltration by T lymphocytes." (PMID 36713375, 2022). "HECTD3 depletion downregulates expression of adhesion molecules, such as VCAM-1, ICAM-1 and E-selectin, in mouse primary ECs and HUVECs stimulated by inflammatory factors and inhibits adhesion of tumor cells to ECs both in vitro and in vivo." (PMID 35918322, 2022). "Along similar lines, tumor cells expressing miR-296-3p inhibit the expression of intercellular adhesion molecule 1 (ICAM-1), which is the ligand of β2 integrin lymphocyte function-associated antigen 1 (LFA-1), providing activating signals to NK cells." (PMID 36560427, 2022). "In response to tumor cell invasion, hsa_circ_0007456 can regulate ICAM-1 expression via miR-6852-3p, thereby regulating natural killer (NK) cell activity to mediate tumor immune escape." (PMID 35464462, 2022). "The function of ICAM1 was found to be correlated with tumor cell adhesion, cell growth signaling pathway, and the transport of immune cells to inflammation sites." (PMID 35935930, 2022). "circ0007456 acts as a sponge of miR-6852-3p, which can affect ICAM-1, a cell surface glycoprotein and an adhesion receptor that can regulate tumor development and metastasis." (PMID 36238299, 2022).
tumor (continued). "Currently, antibodies against the intercellular adhesion molecule-1 were shown to reduce B cell invasion, demonstrating that B cells have the potential to be addressed in tumor progression." (PMID 35250490, 2022). "In fact, the decrease on tumor cell recognition by blocking ICAM-1/LFA-1 interaction was strongly dependent on the concentration used." (PMID 35079096, 2022). "TNF-α can regulate ICAM‐1 expression, which results in enhanced lymphocytic infiltration and tumor apoptosis." (PMID 36505809, 2022). "Instead, they favor tumor-promoting adhesion interaction such as ICAM1 to interact with immune cells such as DCs." (PMID 35874770, 2022). "Activation of LFA-1 on tumor-trafficking T cells to increase binding to ICAM-1 is a potential strategy to increase the recruitment of tumor-specific T cells to the TME." (PMID 35552271, 2022). "By upregulating both ICAM-1 and B7-2, along with MHC-I, CDK4/6 inhibitors thus render the tumor cells susceptible both to T cell killing and to certain types of NK cell killing." (PMID 35562811, 2022). "Several genes coding for cell adhesion molecules (CAMs), which are involved in tumor angiogenesis (i.e., ICAM1, PECAM1, and VCAM1), were highly expressed by OERCs of MCC cells—especially MCC14/2." (PMID 35205840, 2022). "Changes in tumor EC properties under inflammatory conditions with direct consequences for leukocyte tumor infiltration are altered expression of P- and E-selectin, ICAM-1 and ICAM-2, VCAM-1 and CD31/PECAM-1." (PMID 35216427, 2022). "Instead of Treg depletion, we installed an E0771 tumor in a distal mammary fat pad (i.e., left mammary fat pad) 10 days before either control or ICAM-1 KO E0771 cells were implanted in the right mammary fat pad." (PMID 35911772, 2022). "IFNγ is known to upregulate ICAM-1 expression on tumor cells by triggering a signaling pathway dependent on the phosphorylation of STAT-1." (PMID 35681548, 2022). "Intercellular adhesion molecule 1 (ICAM1) is a transmembrane glycoprotein in the immunoglobulin superfamily that plays an important role in cell adhesion of tumor cells and TAMs and signal transduction." (PMID 36059952, 2022). "During tumor metastasis, hepatic endothelial cells represent the first barrier interacting with arriving cancer cells via surface receptors like E-selectin, ICAM1 or Clec4g." (PMID 36496412, 2022). "We found that ICAM-1 expression was high in fibroblasts (i.e., mesenchymal cells of tumor tissue) of tumor tissue in patients with different clinical stages, which negatively correlated with patient survival, consistent with our results in vivo and in vitro." (PMID 36016615, 2022). "Among them, ICAM-1, a cell surface glycoprotein and adhesion receptor, can easily influence inflammatory responses and strongly impacts tumor cell survival and propagation." (PMID 35928884, 2022). "The sensitization to activated cytotoxic lymphocytes is mainly mediated by the increase on ICAM-1 levels, which favors cytotoxic lymphocytes binding to tumor cells." (PMID 35079096, 2022). "EGF facilitated the adhesion of EGFR+ tumor cells with TAMs through ICAM-1–αMβ2 integrin interaction." (PMID 35682890, 2022). "Macrophages can be induced to M2-TAM by tumor cell–derived C-C motif chemokine ligand 2 (CCL-2), transforming growth factor beta (TGF-β), and intercellular adhesion molecule 1 (ICAM-1) and then enhance the malignant phenotype of tumor cells." (PMID 35739593, 2022). "Recent studies have shown that ICAM-1 expression is strongly correlated with poor survival and is known to promote tumor metastasis by regulating various signaling pathways in many cancer types." (PMID 35487888, 2022). "At present, various tumor cells have been shown to highly express ICAM-1 that is known to be a potent ligand for LFA-1 on CTLs." (PMID 36016615, 2022). "Especially, ICAM1, THY1, and CXCR4 showed strongly positive correlations with tumor-associated macrophages." (PMID 34113647, 2021).
tumor (continued). "In a mouse model of sarcoma, pleomorphic neutrophils were found to reduce the expression of intercellular adhesion molecule 1 in tumor cells, thereby increasing tumor motility and facilitating the initiation of metastasis." (PMID 34977870, 2021). "This cycle is based on CX3CL1/ICAM-1-mediated NSCLC cell-VBMEC interactions resulting in enhanced tumor cell aggressiveness and adhesion, improved VBMEC permeability, and increased NSCLC cell transendothelial migration through several signaling pathways." (PMID 33754027, 2021). "There are reports suggesting that ICAM-1 molecules enable cancer cells to avoid the immune system, enhance tumor growth, and angiogenesis." (PMID 34680113, 2021). "The downregulation of adhesion molecules, such as vascular cell adhesion molecule 1 (VCAM1) and intercellular adhesion molecule 1 (ICAM1), in the tumour microenvironment can inhibit T cell migration to the tumour site." (PMID 34281259, 2021). "IL6 enhanced lung colonization of OS cells by overexpression of ICAM-1 and promoted tumor metastasis." (PMID 33436536, 2021). "ICAM-1 is commonly expressed on immune cells although expression on tumor cell surface has been demonstrated." (PMID 34831294, 2021). "Some NF-κB target genes such as CCND1, BCL2L1 and GADD45B and ICAM1 which are responsible for proliferation, anti-apoptosis and adhesion were also upregulated in the tumor tissues." (PMID 33144684, 2021). "Leucocyte infiltration into the tumor requires interactions with several EC receptors, selectins, ICAM1 and VCAM1." (PMID 34073394, 2021). "On mouse models, the ICAM1-LFA-1 interaction was also shown to cause clusters of activated T cells in the tumor and was suggested as a mechanism of tumor-mediated immune retention that prevents trafficking of T cells to lymph nodes." (PMID 34430923, 2021). "The excessive activation of VEGF-VEGFR pathways can directly inhibit the trafficking of immune cells to the tumor by inhibiting upregulation of the expression of intercellular adhesion molecule-1(ICAM-1) and vascular cell adhesion molecule-1(VCAM-1)." (PMID 33791214, 2021). "When injected with the ICAM-1 antibody, the number of tumor masses of the DAC group was less than the DAC + ICAM-1 antibody group (p = 0.0023)." (PMID 34722306, 2021). "ICAM-1 not only participates in the recognition and killing of tumor cells by immune cells but also plays a certain role in the process of tumor evading the body’s immunity." (PMID 34386034, 2021). "The expression levels of CXCL10, IGF1, MMP3, MMP1, ICAM1, and IL-13 were significantly up-regulated in tumor tissues." (PMID 34544905, 2021). "Hallmarks of a gradual dedifferentiation of HECs correlating with tumor progression included reduced expression of PNAd, ICAM-1, CCL21, and the ectoenzyme ATX." (PMID 34706240, 2021). "We anticipate that this model will be useful in determining the effects of anti-viral immunity on anti-tumor immunity in relation to other picornaviruses that exploit ICAM-1 for infection." (PMID 34503272, 2021). "ICAM-1 is commonly expressed at high levels on tumor cells, which seems to be responsible for the tropism of CVA21 to a wide variety of cancers." (PMID 33919076, 2021). "Tumor necrosis factor receptor-associated factor 4 (TRAF4), an RING E3 ligase, promotes secretion of soluble intercellular adhesion molecule 1 (sICAM1) in normal fibroblasts, which induces angiogenesis and tumor progression." (PMID 33466790, 2021). "Overproduction of pro-angiogenic factors such as VEGF in tumours can result in a decrease in the expression of adhesion molecules such as ICAM-1 and 2, VCAM-1, and CD34." (PMID 33917287, 2021). "We also highlight hsa_circ_0007456/miR-6852-3p/ICAM-1 axis as an important signaling pathway in the process of tumor immune evasion and the tumorigenesis of HCC." (PMID 33462208, 2021).
tumor (continued). "ICAM-1 can not only mediate the nonspecific adhesion between tumor cells and T cells and facilitate the recognition of tumor cells by T cells but also bind to the LFA-1 ligand on the surface of T cells to form a complex ICAM-1/LFA-1." (PMID 34386034, 2021). "Leukocytes express LFA‐1 and Mac‐1 on their surface, which are receptors for intercellular adhesion molecule 1 (ICAM‐1) that is highly expressed in inflamed endothelial cells and metastatic tumor cells." (PMID 33898169, 2021). "EGF was also observed to increase αMβ2 integrin on TAMs and ICAM-1 on tumor cells, promoting the adhesion between TAMs and tumor cells." (PMID 34717710, 2021). "IL-8 provokes the expression of integrin αM on neutrophils that can interact with intercellular adhesion molecule 1 (ICAM1) expressed by tumor cells and results in the adherence of tumor cells to the liver sinusoids and the formation of metastatic foci." (PMID 32902664, 2021). "As proof-of-concept, anti-ICAM1 neutralizing antibody can effectively block tumor cell cluster formation and TEM, thereby inhibiting lung metastasis." (PMID 34381029, 2021). "The binding of LFA-1 to intercellular adhesion molecule-1 (ICAM-1) on tumor cells induces lytic granule polarization and NK-cell-mediated cytolysis." (PMID 34660784, 2021). "That is, zebularine allows for the re-expression of intercellular adhesion molecule-1 (ICAM-1) on tumor endothelial cells, which results in restored leukocyte-endothelial cell adhesion and enhanced leukocyte infiltration." (PMID 34575678, 2021). "Critical to this work is the discovery that Th1 cells expressed adhesion molecules LFA-1/ICAM-1, that allow transmigration into tumor tissues across tumor vessels, supporting tumor metastasis." (PMID 33669271, 2021). "ICAM1, also known as CD54, is established to mediate the adhesion of malignant epithelial cells to the lymphatic endothelium and, therefore, promote the tumor spread in regional lymph nodes." (PMID 33562532, 2021). "ICAM1 is involved in tumor cell adhesion to vascular endothelium or neutrophils, and mediates the hematogenous and lymph node metastasis of malignant tumors." (PMID 34544905, 2021). "Antibiotic-induced dysbiosis enhances distal tumor progression through ICAM-1-mediated suppression of effector CD8+ T-cell trafficking into the tumor." (PMID 35011369, 2021). "Other studies have also shown an involvement of tumour cell ULBPs or ICAM-1 expression, or activating receptors NKG2D and DNAM-1 in mediating Vδ1 cytotoxicity." (PMID 34944832, 2021). "Together with the findings here we can draw the conclusion that IL-6 inhibits tumor growth by promoting the expression of E/P-selectin and ICAM-1 via JAK/STAT3 pathway and consequently facilitating T cells infiltration." (PMID 33390844, 2021). "The next anti-tumour activity of radiotherapy can occur by introducing Fas ligands expression and ICAM-1 molecule on tumour cells, making tumour cells more sensitive to T cell-mediated lysis." (PMID 34281259, 2021). "In melanoma, ICAM-1 expressed in TECs interacts with its receptor integrin LFA-1 to promote tumor cell migration across the endothelium in vitro." (PMID 34988011, 2021). "RT induced up-regulation of ICAM-1 to enhance both the activation and tumor infiltration of CD8+ T cells." (PMID 35095911, 2021). "It has shown that ICAM-1 CAR T cells mediated ATC tumor killing were of validation in vitro and in animal models." (PMID 34900720, 2021). "Due to the increased expression of tumor necrosis factor‐alpha (TNF‐α) and intercellular adhesion molecule 1 (ICAM‐1), N1 (anti‐tumor) phenotype neutrophils are cytotoxic toward tumor cells." (PMID 34390218, 2021). "In conclusion, we identify here hsa_circ_0007456 as a promising biomarker of HCC, and highlight hsa_circ_0007456/miR-6852-3p/ICAM-1 axis as an important signaling pathway in the process of tumor immune evasion and the tumorigenesis of HCC." (PMID 33462208, 2021).
tumor (continued). "Here, TAMs within the spheroids secrete epidermal growth factor (EGF) and lead to upregulation of integrin and intercellular adhesion molecule 1 (ICAM‐1) in tumor cells." (PMID 34060699, 2021). "Necrosis can release cancer-promoting factors like MMP1, HMGB1, and ICAM1, which induce microenvironment changes resulting in tumor aggressiveness." (PMID 34084172, 2021). "We also overexpressed ICAM1 into L2G-labeled ICAM1-negative TN1 PDXs for sorting of ICAM1-overexpressing (ICAM1+ OE) and ICAM1− tumor cells for clustering assay." (PMID 34381029, 2021). "It is important to note that this rafting effectis typical for various surface receptors, in particular tumor markerssuch as folate and transferrin receptors or ICAM-1." (PMID 34179645, 2021). "Depletion of ICAM1 abrogates lung colonization of TNBC cells by inhibiting homotypic tumor cell-tumor cell cluster formation." (PMID 34381029, 2021). "The interaction of MUC1 and ICAM1 promotes the migration of cancer cells and increases the invasive potential of tumor cells." (PMID 34770912, 2021). "This also caused heterotypic aggregation between these two cell types, which was inhibited by ICAM1 knockdown in both tumor cells and endothelial cells." (PMID 34381029, 2021). "Previous studies in mouse tumour models of post-surgical adjuvant therapy demonstrated that an increase in Ang-2–mediated ICAM-1 expression contributed to the observed increase in CCL2-induced recruitment of tumour-promoting CCR2+Tie2− macrophages." (PMID 33564135, 2021). "As increased ICAM-1 expression stimulates NK cell-mediated killing due to strengthened interactions of NK cells and targets, we next investigated NK cell-mediated tumor killing." (PMID 33140189, 2021). "A tight adherence of neutrophils and tumor cells via the tumor-expressed ICAM-1 activates the neutrophils, weakens the endothelial barrier, and enhances the extravasation of CTCs." (PMID 33670434, 2021). "To further evaluate the role of ICAM1 in tumorigenesis with a series of cell dilutions, we sorted the ICAM1+ (OE) and ICAM1− tumor cells from these transduced PDXs (originally ICAM1−/low)." (PMID 34381029, 2021). "We found that inhibition of VEGF with mcr84 elevated the expression of VCAM-1 and ICAM-1 on tumor endothelium in 4T1 tumors." (PMID 34673569, 2021). "We found that the infiltration of mDCs in tumor tissues can be promoted by the expression of ICAM1 and interaction with ITGAM expressed in macrophages." (PMID 34876143, 2021). "ECs activation is characterized by increased expression of surface adhesion molecules such as VCAM1 and ICAM1 and there is evidence that VCAM-1 is closely associated with tumor neoangiogenesis and progression." (PMID 33853689, 2021). "In fact, T cells express several other receptors, such as β1 and β2 integrins, which can bind to immunoglobulin superfamily ligands (e.g., ICAM-1) on various tumor cells or other cells to form immuno-oncologic synapses." (PMID 34944831, 2021). "Some studies have corroborated the positive relevance between the expression level of E/P-selectin as well as ICAM-1 and tumor metastasis." (PMID 33390844, 2021). "ICAM-1 is also a target of miR-296-3p, which enables invasiveness, intravasation, and enhances the survival of NK-resistant circulating tumor cells." (PMID 33321819, 2020). "Another study revealed that leptin provoked the JAK1/2, STAT3, FAK, ERK, and GSK3αβ signaling cascade to stimulate the production of soluble ICAM-1 in cancer cells, which induced osteoclast formation and enhanced tumor-induced osteolysis in vivo." (PMID 33371368, 2020). "A mechanism by which fibrin connects ICAM-1 on tumor cells to integrin αIIbβ3 on platelets has been particularly highlighted." (PMID 32575608, 2020). "In previous studies, Guo and his colleagues provided evidence that the in vitro TNBC cell-ICAM1 antibody binding force on live cells correlated with the in vivo tumor accumulation and therapeutic efficacy of ICAM1 antibody-directed liposomes." (PMID 33072116, 2020).